PSMB10 (proteasome 20S subunit beta 10)
Description:
The proteasome is a multicatalytic proteinase complex which is characterized by its ability to cleave peptides with Arg, Phe, Tyr, Leu, and Glu adjacent to the leaving group at neutral or slightly basic pH. The proteasome has an ATP-dependent proteolytic activity. This subunit is involved in antigen processing to generate class I binding peptides.
Synonyms: LMP10; MECL1; MGC1665; beta2i; IMD121; PRAAS5
Tractability: Small molecule: an approved drug acts on it; a structure with a bound ligand is known; a high-quality ligand is known; it belongs to a druggable protein family. PROTAC: ubiquitination databases record sites on it; its protein half-life has been measured; a small molecule that binds it is known.
Target class: Threonine protease; Protease; Threonine protease T1A subfamily; Threonine protease PBT clan; Enzyme
Gene: Protein-coding gene on chromosome 16 (67,934,506 to 67,936,864, reverse strand). Ensembl gene ENSG00000205220.
Subcellular location: Cytoplasm; Nucleus
Subcellular location (Human Protein Atlas): Cytosol; Vesicles
Pathways (Reactome):
Immune System: Antigen processing: Ub, ATP-independent proteasomal degradation; Cross-presentation of soluble exogenous antigens (endosomes); ER-Phagosome pathway
Metabolism of proteins: Proteasome assembly
Gene Ontology:
Molecular function: protein binding; endopeptidase activity; threonine-type endopeptidase activity
Biological process: antigen processing and presentation of exogenous peptide antigen via MHC class I, TAP-dependent; CD8-positive, alpha-beta T cell differentiation; CD8-positive, alpha-beta T cell homeostasis; humoral immune response; immune system process; negative regulation of regulatory T cell differentiation; positive regulation of interleukin-2 production; positive regulation of tumor necrosis factor production; positive regulation of type II interferon production; proteasomal protein catabolic process; proteasomal ubiquitin-independent protein catabolic process; proteasome-mediated ubiquitin-dependent protein catabolic process; response to type II interferon; T-helper 1 cell differentiation; T-helper 17 cell differentiation; thymic T cell selection; protein catabolic process
Cellular component: proteasome complex; cytosol; nucleus; proteasome core complex; proteasome core complex, beta-subunit complex; spermatoproteasome complex; cytoplasm
Genetic constraint (gnomAD): Loss-of-function variants: 29 observed, 30.43 expected, observed/expected ratio (o/e) 0.95, 90% interval 0.71 to 1.3. The upper end of that interval is the gene's LOEUF score, 1.3, which puts it in group 5 of 6, group 1 being the genes least tolerant of losing a copy. Missense variants: 327 observed, 377.82 expected, observed/expected ratio (o/e) 0.87, 90% interval 0.79 to 0.95. Synonymous variants: 157 observed, 171.15 expected, observed/expected ratio (o/e) 0.92, 90% interval 0.81 to 1.05.
Gene-disease validity (ClinGen):
ClinGen rates the evidence that PSMB10 causes each of these diseases.
immunodeficiency 121 with autoinflammation (autosomal dominant): Limited.
Homologues: Orthologues: chimpanzee PSMB10 (100% identical), macaque PSMB10 (96% identical), mouse Psmb10 (89% identical), guinea pig PSMB10 (88% identical), rabbit PSMB10 (88% identical), dog PSMB10 (86% identical), pig PSMB10 (85% identical), rat Psmb10 (79% identical), zebrafish psmb10 (64% identical), tropical clawed frog psmb7.2 (60% identical), Drosophila melanogaster Prosbeta1 (23% identical), Caenorhabditis elegans pbs-1 (21% identical). Paralogues in human: PSMB7 (58% identical), PSMB9 (24% identical), PSMB6 (23% identical), PSMB11 (22% identical), PSMB8 (21% identical), PSMB5 (20% identical), PSMA5 (18% identical), PSMB1 (18% identical), PSMA1 (18% identical), PSMA4 (18% identical), PSMB2 (17% identical), PSMB4 (17% identical), and 6 more.
Diseases named in the same sentence as PSMB10 in open-access papers:
PSMB10 is named in the same sentence as 90 diseases in open-access papers, as found by Europe PMC text mining. Sharing a sentence is not in itself a finding about the gene and the disease. The quoted sentences say what the papers report.
melanoma (7 papers, 2010 to 2025). A malignant, usually aggressive tumor composed of atypical, neoplastic melanocytes. "Immunohistochemical detection showed that PSMB10 was positive in the two malignant melanoma specimens, a positive rate of 100%." (PMID 34220795, 2021). "At the same time, we supplemented 15 quantitative immunohistochemical analyses of melanoma and paracancerous tissues, and the results showed that the IOD/Area of PSMB10 in paracancerous samples was higher." (PMID 34220795, 2021).
bladder cancer (4 papers, 2020 to 2025). "LC1 tumours also showed modest enrichment for immune‐associated transcripts, including CCL15 and PSMB10, and elevated RNH1 expression, a gene previously linked to reduced invasion and metastasis in bladder cancer." (PMID 41425537, 2025). "Future studies using functional bladder cancer models, molecular assays, activity-based probes, and single-cell approaches are needed elucidate PSMB10’s mechanistic role in tumor–immune interactions." (PMID 41222746, 2025).
breast carcinoma (4 papers, 2018 to 2025). "To investigate if the revealed differences in gene expression correlate with the amount of proteasome subunits in cancer cells, we analyzed the relative levels of mRNAs encoding the immunoproteasome subunits PSMB8, PSMB9 and PSMB10 in four breast cancer cell lines: MCF-7, SKBR3, ZR-75-1 and BT-474." (PMID 39796785, 2025). "PSMB10 was also reported to be lower in metastatic breast cancer compared to primary breast cancer." (PMID 35693739, 2022). "Besides, HECTD3, PSMB10, UBD, UBE2C, and UBE2S involved in the ubiquitin proteasome pathway, as well as CCL2, CCR1, CXCL10, CXCL11, and IL2RG implicated in the cytokine–cytokine receptor interaction pathway, might be used for evaluating the efficacy of neoadjuvant chemotherapy in breast cancer." (PMID 29685151, 2018). "These suggested that HECTD3, PSMB10, UBD, UBE2C, and UBE2S might also affect the efficacy of neoadjuvant chemotherapy in breast cancer through the ubiquitin proteasome pathway." (PMID 29685151, 2018).
Immunodeficiency (4 papers, 2018 to 2022). Failure of the immune system to protect the body adequately from infection, due to the absence or insufficiency of some component process or substance. "Although the detailed molecular mechanisms are still unknown, it can be assumed that PSMB9 G156D and PSMB10 G209W should lead to defective interaction of two β rings and impaired formation of the 20S complex thereby causing immunodeficiencies." (PMID 34819510, 2021). "Effects of PSMB10 G209W to induce immunodeficiency seem milder than those of PSMB9 G156D." (PMID 34819510, 2021).
COVID-19 (3 papers, 2021 to 2023). A disease caused by infection with severe acute respiratory syndrome coronavirus 2. "Regarding the expression of 20S subunits in the α- and β-ring the mRNA expression of PSMA4, PSMA5, PSMB2, PSMB9, PSMB10 significantly increased in COVID-19 patients (COV) when compared to healthy control (HC)." (PMID 35327634, 2022). "Interestingly, we only observed an increase in PSMB9 and PSMB10, suggesting mediation of the immunoproteasome in COVID-19 pathology." (PMID 35327634, 2022). "Specifically, along with CD68, the immunoproteasome-related genes PSMB8, TAP1, PSMB9, PSMB10, and calreticulin (CALR) were all found to be expressed in the CD14+/CD16+ subpopulation of cells during mild COVID-19." (PMID 34225749, 2021).
endometrial cancer (3 papers, 2019 to 2021). Primary or metastatic malignant neoplasm involving the endometrium (mucous membrane that lines the endometrial cavity). "PSMB10 has also been shown to be a prognosis-related Hub gene in endometrial cancer." (PMID 34868920, 2021). "We selected the six hub genes (GTSE1, BIRC5, AURKA, PBK, KNSTRN, and PSMB10) and AKT1 to evaluate gene expression values in endometrial cancer using IHC." (PMID 31781484, 2019).
leukemia (3 papers, 2024 to 2025). A malignant (clonal) hematologic disorder, involving hematopoietic stem cells and characterized by the presence of primitive or atypical myeloid or lymphoid cells in the bone marrow and the blood. "To investigate the role of PSMB10 in leukemia maintenance, we first used short hairpin RNA (shRNA) to KD PSMB10 expression (shPSMB10) in two human AML cell lines (THP-1 and KG-1a)." (PMID 40462177, 2025). "By testing the percentage of GFP+ leukemia cells in the PB of mice at 1–2 weeks after 1st transplantation, we found that Psmb10 depletion reduced the leukemia burden in the PB of these mice." (PMID 40462177, 2025). "High PSMB10 maintained leukemia stemness, immune evasion; inactivation promoted senescence, drug uptake, restored CTL killing." (PMID 41293269, 2025). "PSMB10 sustains resistant stem-like leukemia pools; inhibition therapeutic." (PMID 41293269, 2025). "As we used AraC to induce leukemia senescence, we discovered that the downregulation of PSMB10 increased SA-β-Gal activity, the proportion of cells in G0/G1 phase and SASP factor levels, and decreased cell cycle-associated gene expression in different AML cell lines." (PMID 40462177, 2025). "Furthermore, the downregulation of PSMB10 hindered the initiation of leukemia and the maintenance of LSC with a 19-fold reduction in the frequency of human LSCs in the human-to-mouse leukemia cell transplantation model." (PMID 40462177, 2025). "Similarly, AML research has shown that high PSMB10 maintains leukemia stemness and immune evasion, but inactivation triggers senescence, drug internalization, and reactivates CTL-mediated killing." (PMID 41293269, 2025). "The increased PSMB10 promotes the stemness maintenance of chemotherapeutic drug-resistant leukemia cells via the inhibition of SLC22A16-mediated drug endocytosis and RPL6/RPS6-MDM2-P21 pathway-initiated senescence, as well as the MHC-I protein degradation-induced escape of CTL killing." (PMID 40462177, 2025). "The results showed that β2m KD led to decreased MHC-I molecule levels with decreased CTL killing of leukemia cells, suggesting that increased PSMB10 results in leukemia cell resistance to CTL-mediated killing through the direct interaction and ubiquitinated degradation of MHC-I protein." (PMID 40462177, 2025). "To further determine whether PSMB10 maintained the stemness of leukemia cells via immune escape, we cocultured THP-1 or KG-1a cells transfected with the indicated lentivirus and activated healthy human CD3+ T cells for 18 h at different effector/target ratios (E: T)." (PMID 40462177, 2025). "Additionally, a marked decrease in the percentage of GFP+ leukemic cells was noted in the BM, spleen, and PB of the 2nd recipient mice transplanted with AraC- and ADM-treated Psmb10−/− MA9 mouse BM leukemia cells, compared to those receiving Psmb10+/+ MA9 cells." (PMID 40462177, 2025). "Since chemotherapy induces the senescence of leukemia cells partly via P21, combined with our discovery that PSMB10 induces MDM2-mediated degradation of P21 protein, we conclude that the increased PSMB10 also impedes chemotherapy drug-induced P21-dependent senescence of AML cells." (PMID 40462177, 2025). "We found that PSMB10 KD significantly sensitized AML cells to CTL killing, and this cytotoxicity was effectively rescued upon restoration of PSMB10 expression, suggesting that PSMB10 promotes the escape of leukemia cells from CTL-mediated killing." (PMID 40462177, 2025). "To further investigate whether PSMB10 downregulation could increase primary LSC sensitivity to chemotherapy in vivo with syngeneic normal hematopoietic and immune microenvironment, we used the MLL-AF9 (MA9) leukemia mouse model." (PMID 40462177, 2025).
leukemia (continued). "Although a recent study revealed that the immunoproteasome subunit PSMB8 maintains oncogenic gene expression in KMT2A complex-driven leukemia, we first found that the increased PSMB10 but not PSMB8 is involved in chemotherapeutic drug-resistant LSC maintenance via senescent and immune regulation." (PMID 40462177, 2025).
virus infection (3 papers, 2016 to 2025). "Of note, immunoproteasome subunit beta types PSMB8, PSMB9, and PSMB10, together with the PSME2 subunit of the immunoproteasome specific regulatory 11S cap structure, strongly indicated increased levels of immunoproteasomes with progressing virus infection." (PMID 37112941, 2023). "While we found that stimulation with exogenous IFNs could induce PSMB8, PSMB9 and PSMB10 expression in both cell lines, neither could produce the cytokines upon virus infection." (PMID 40872920, 2025).
combined immunodeficiency (2 papers, 2018 to 2022). A broad classification of inherited disorders presenting at birth that affect both the cell-mediated and humoral aspects of the immune response. "In addition, it has been shown in mice that another homozygous PSMB10 variant (p.Gly170Trp) could induce severe combined immunodeficiency (SCID) and systemic autoinflammation, while heterozygous mice only had a T cell defect." (PMID 36250618, 2022). "In addition, a private de novo missense variant in PSMB10 was found in a patient with Omenn syndrome with severe combined immunodeficiency (SCID), ectodermal dysplasia, alopecia, hypodontia and anonychia (patient 1)." (PMID 36250618, 2022).
cutaneous melanoma (2 papers, 2020 to 2021). A primary melanoma arising from atypical melanocytes in the skin. "IRF1, PSMB9, TAP1, ETV7, and PSMB10 were related to CD8+ T cell infiltration proportion in thyroid carcinoma, breast invasive carcinoma, head and neck squamous cell carcinoma, hepatocellular carcinoma, lung adenocarcinoma, and skin cutaneous melanoma." (PMID 33330025, 2020).
glioma (2 papers, 2021 to 2024). A benign or malignant brain and spinal cord tumor that arises from glial cells (astrocytes, oligodendrocytes, ependymal cells). "Numerous studies have demonstrated the regulatory roles of PSMB8, PSMB9, and PSMB10 in glioma proliferation, migration, angiogenesis, inflammatory response, and hypoxia-related tumor characteristics." (PMID 39619148, 2024). "The results showed that PSMB6, PSMA5, UBB, and PSMD12 were highly expressed in the glioma tissues, while PSMB10 was lowly expressed in the glioma tissues compared with the normal tissues." (PMID 34868920, 2021). "The results showed that PSMB6, PSMA5, UBB, and PSMD12 were significantly downregulated, and PSMB10 was significantly upregulated in gliomas." (PMID 34868920, 2021). "In the present study, PSMA5 and PSMB6 were found to be highly expressed in gliomas, while PSMB10 was found to be lowly expressed by integrating the TCGA and GTEx databases’ glioma sample analyses." (PMID 34868920, 2021). "In addition, PSMB6, PSMA5, UBB, and PSMD12 were lowly expressed, while PSMB10 was highly expressed, in the TCGA and GTEx integrated glioma samples and normal samples, which were verified through protein expression levels in the Human Protein Atlas database." (PMID 34868920, 2021). "This study found the prognostic predictive values of the hypoxia-related genes PSMB10, PSMD12, UBB, PSMA5, and PSMB6 for glioma and provided ideas and entry points for the progress of hypoxia-related glioma." (PMID 34868920, 2021). "Univariate and multifactorial COX regression analyses were used to determine that PSMB10, PSMD12, UBB, PSMA5, and PSMB6 may be independent prognostic factors for gliomas." (PMID 34868920, 2021). "In this study, our objective was to analyse whether SMB6, PSMD9, UBB, PSMD12, PSMB10, PSMA5, and PSMD14 are independent prognostic factors for glioma." (PMID 34868920, 2021). "PSMB10, PSMD12, UBB, PSMA5, and PSMB6 were found to be independent predictors of glioma prognosis." (PMID 34868920, 2021). "Notably, PSMB10, PSMD12, UBB, PSMA5, and PSMB6 were found to be independent prognostic predictive markers for glioma." (PMID 34868920, 2021).
Omenn syndrome (2 papers, 2022 to 2025). An inflammatory condition characterized by erythroderma, desquamation, alopecia, chronic diarrhea, failure to thrive, lymphadenopathy, and hepatosplenomegaly, associated with severe combined immunodeficiency (SCID). "Limited V(D)J recombination was also observed in patients with PSMB10-associated Omenn syndrome (PSMB10) and tricho-hepato-enteric syndrome due to SKIV2L variants (SKIV2L), although the exact contribution of both proteins to human V(D)J recombination remains to be determined." (PMID 41607487, 2025).
acute pancreatitis (1 paper, 2024). An acute inflammatory process that leads to necrosis of the pancreatic parenchyma. "We found that all genes from the TIS were statistically significant between the Ehmt2fl/fl pancreas compared to the Ehmt2+/+ controls during acute pancreatitis, with a range from 0.34 for Psmb10 as the least log2 FC to 3.48 for Tigit with the most significant change." (PMID 38948355, 2024).
acute promyelocytic leukemia (1 paper, 2021). An aggressive form of acute myeloid leukemia (AML), characterized by arrest of leukocyte differentiation at the promyelocyte stage, due to a specific chromosomal translocation t(15;17) in myeloid cells. "β2i, or MECL1, encoded by PSMB10, has been reported to be downregulated in metastatic breast carcinoma, NSCLC, and acute promyelocytic leukemia however its functional relevance in tumor development is yet to be determined." (PMID 34944095, 2021).
anemia (1 paper, 2021). A reduction in the number of red blood cells, the amount of hemoglobin, and/or the volume of packed red blood cells. "Further, through a study of anemia caused by congenital red blood cell aplasia in human, PSMB10 has been suggested to be functional in the MHC class I machinery in mature red blood cells in response to inflammatory signaling." (PMID 34256695, 2021).
cervical cancer (1 paper, 2018). A primary or metastatic malignant neoplasm involving the cervix. "A set of key risk factors anaerococcus, hydrogenophilaceae, eubacterium, PSMB10, KCNIP1 and KRT13 have been identified, which are thought to be involved in the regulation of viral response, cell cycle and epithelial cell differentiation in cervical cancer." (PMID 29745858, 2018).
gastric cancer (1 paper, 2023). A primary or metastatic malignant neoplasm involving the stomach. "A final and significant outcome of our study is the identification of a restricted number of genes which are up-regulated (IRF1, CTSS, PSMB10, CYP26B1, DHRS3 and TINAGL1) and down-regulated (AHNAK2) by ATRA in all the retinoid-sensitive gastric-cancer cell-lines considered." (PMID 37951921, 2023).
idiopathic inflammatory myopathies (1 paper, 2022). "Previous research reported that PSMB8, PSMB9 and PSMB10 expressed at significantly abundant levels in dendritic cells, monocytes, and CD8+ T-cells in idiopathic inflammatory myopathies, which correlated highest with STAT1, IRF1 and IFN-γ expression." (PMID 35933405, 2022).
myositis (1 paper, 2014). "Relative quantification of proteasomal subunit expression by real time RT-PCR revealed a myositis related significant increase of at least one of the immunoproteasomal subunits PSMB8, PSMB9 and/or PSMB10 in all investigated cellular subsets except CD4+." (PMID 25098831, 2014).
nasopharyngeal carcinoma (1 paper, 2020). A carcinoma arising from the nasopharyngeal epithelium. "Specifically speaking, in nasopharyngeal cancer cells, the results of microarray profiles indicated that miR-9 could target several APM components including TAP1, LMP8 (also termed PSMB8), LMP9 (PSMB9), LMP10 (PSMB10), and β2-microglobulin." (PMID 32222150, 2020).
sarcoma (1 paper, 2023). A usually aggressive malignant neoplasm of the soft tissue or bone. "Particularly, the expression levels of other proteasome pathway genes, including PSMC1, PSMB6, PSMC2, and PSMB10 seemed to be differentially expressed in MFS/US sarcomas." (PMID 37185612, 2023).